EFCAB8 (EF-hand calcium binding domain 8)
Tractability: No criterion of Open Targets' tractability assessment is met for any kind of drug.
Gene: Protein-coding gene on chromosome 20 (32,858,923 to 32,961,845, forward strand). Ensembl gene ENSG00000215529.
Gene Ontology:
Molecular function: calcium ion binding
Genetic constraint (gnomAD): Loss-of-function variants: 76 observed, 97.23 expected, observed/expected ratio (o/e) 0.78, 90% interval 0.65 to 0.95. The upper end of that interval is the gene's LOEUF score, 0.95, which puts it in group 4 of 6, group 1 being the genes least tolerant of losing a copy. Missense variants: 1,161 observed, 1,295.2 expected, observed/expected ratio (o/e) 0.9, 90% interval 0.85 to 0.94. Synonymous variants: 496 observed, 525.21 expected, observed/expected ratio (o/e) 0.94, 90% interval 0.88 to 1.02.
Homologues: Orthologues: chimpanzee EFCAB8 (99% identical), macaque EFCAB8 (92% identical), mouse Efcab8 (60% identical), rat Efcab8 (60% identical), Caenorhabditis elegans sel-10 (6% identical), tropical clawed frog XB1017155 (4% identical). Paralogues in human: WDR49 (19% identical), WDR64 (14% identical), FBXW7 (9% identical), TRAF7 (7% identical), FBXW11 (7% identical), BTRC (7% identical), FBXW8 (5% identical), FBXW9 (5% identical), WDR86 (5% identical), FBXW12 (4% identical), WDR54 (3% identical), PAAF1 (3% identical), and 2 more.